IL4 (interleukin 4)
Diseases named in the same sentence as IL4 in open-access papers (continued):
Sharing a sentence is not in itself a finding about the gene and the disease.
pulmonary fibrosis (continued). "However, recent studies have shown that Th9 cells do contribute to pulmonary fibrosis by increasing IL-4-mediated Th2 cell differentiation, and IL-9 neutralisation effectively reduces the degree of pulmonary fibrosis." (PMID 36232511, 2022). "We also found that Th9 cells promote pulmonary fibrosis via IL-9 and IL-4 mediated pathways." (PMID 34831433, 2021). "In brief, actions of some of the assessed interleukins in the context of pulmonary fibrosis can be summarized as follows: IL1ꞵ (pro-fibrotic), IL4 (pro and anti-fibrotic), IL6 (pro and anti-fibrotic), IL8 (pro-fibrotic), IL10 (anti-fibrotic), IL12 (anti-fibrotic), and IL13 (pro-fibrotic)." (PMID 34960806, 2021). "In addition, we discovered that Th9 cells also promote pulmonary fibrosis via increasing IL-4-mediated Th2 cell differentiation." (PMID 34831433, 2021). "Our hypothesis is different from regarding Th9/IL-9 as a whole in previous studies, and this study is the first to explore the role of Th9 cells in promoting pulmonary fibrosis via IL-9 and IL-4." (PMID 34831433, 2021). "However, in a different model of pulmonary fibrosis where RELMα–/– mice were treated with bleomycin, these mice exhibited decreased IL-4 expression and less fibrosis in comparison to wild-type mice." (PMID 32471168, 2020). "It was demonstrated that the Th1 cells were predominant and activated in the inflammation period of silicosis and secreted large amounts of IFN-γ to inhibit fibrosis; in fibrosis during silicosis, the Th2 cells were predominant and activated, and they secreted IL-4 to promote pulmonary fibrosis." (PMID 35541981, 2018). "IL-4 deficiency did also not alter the sensitivity of mice to pulmonary fibrosis induced by intratracheal administration of BLM (0.06 mg, 1 mg = 1 U) when investigated at 14 days post BLM-treatment." (PMID 28836991, 2017). "Indeed, IL-4 and IL-13 have been described in lungs from patients with Idiopathic Pulmonary Fibrosis and contribute to the development of fibrosis in a number of mouse models." (PMID 22363610, 2012). "Both IL-4 and IL-13 have redundant signaling pathways with implications in pulmonary fibrosis." (PMID 23283176, 2011). "Furthermore, increased levels of IL-4 were observed in animal models of pulmonary fibrosis and lungs of patients with idiopathic pulmonary fibrosis (IPF) or cryptogenic fibrosing alveolitis." (PMID 16095529, 2005). "However, IL-4 may exert detrimental effects during tissue repair by promoting pulmonary fibrosis through fibroblast activation and collagen deposition." (PMID 41596433, 2026). "For example, interleukin-4 (IL-4) and IL-13 stimulate B lymphocytes to produce IgE and induce smooth muscle contraction responsible for bronchospasm and lung remodeling via hypertrophy and hyperplasia of mucus-producing goblet cells promoting pulmonary fibrosis." (PMID 39507249, 2024). "In vivo macrophage depletion by clodronate liposomes and reinfusion of IL-4-induced M2 bone marrow-derived macrophages (BMDMs) from wild-type mice, combined with in vitro cell experiments, were performed to further validate the mechanism underlying NAMPT involving lung fibrosis." (PMID 38773984, 2024). "However, recent evidence in murine models of lung fibrosis suggests that IL-10 may be profibrotic, exacerbating Th2 responses, producing IL-4 and IL-13, the recruitment of fibrocytes, and M2 macrophage polarization." (PMID 36831337, 2023). "The role of IL-4 in pulmonary fibrosis may be controversial and needs further investigation." (PMID 33723241, 2021). "Furthermore, those more profibrogenic macrophages which play a vital role in airway remodeling in pulmonary fibrosis biases alternatively activated macrophages, so we used IL-4-stimulated BMDMs for in vitro experiments to mimic profibrogenic macrophages in vivo." (PMID 35069531, 2021).
pulmonary fibrosis (continued). "In addition to the redundancy of IL-4 and IL-13 signaling through IL-4Rα/Stat6, IL-13 may signal through a distinct pathway via the IL-13Rα2 driving TGFβ1 dependent pulmonary fibrosis." (PMID 23283176, 2011). "Two studies evaluated the effects of Ginkgo biloba leaf extract on IL-4 and IFN-γ levels in patients with pulmonary fibrosis." (PMID 40110130, 2025). "Next, levels of IL-4, IL-13 and TGF-β1 in BALF of WT and USP25-/-mice after BLM-induced pulmonary fibrosis models were measured by ELISA." (PMID 39781451, 2025). "Depleting monocytes/macrophages in Namptfl/fl;Cx3cr1CreER mice by clodronate liposomes and subsequent pulmonary reinfusion of IL-4-induced M2 BMDMs from wild-type mice, reversed the protective effect of monocyte/macrophage NAMPT-deletion on lung fibrosis." (PMID 38773984, 2024). "The pathogenesis of pulmonary fibrosis involves various mediators such as TGF-β, legumain, osteopontin, IL-4, IL-6, IL-13, IL-17, TNF-α, Gal-1, Gal-3, PDGF, and FGFR-1." (PMID 38540252, 2024). "Meanwhile, IL-4 and IL-13 induce RELMα expression via activating STAT6 in rat AEC II during bleomycin (BLM)-induced lung fibrosis." (PMID 36691020, 2023). "JTE-013 was found to regulate the physiological processes of pulmonary fibrosis and reduce BLM-induced inflammatory pulmonary fibrosis, as evidenced by the results of H&E and Masson staining, and, the expression changes of IL-4, IL-5, IFN-γ, and TNF-α in BALF." (PMID 37895915, 2023). "We show that DNMT3B deficiency promotes alternative macrophage polarization induced by IL4 and TGFB1 in vitro and also enhances profibrotic macrophage polarization in the alveolar space during pulmonary fibrosis in vivo." (PMID 35725453, 2022). "This idea confirms earlier studies showing that TGF-β3 decelerates the progress of radiation-induced pulmonary fibrosis by hindering fibrocyte recruitment and regulating the IFN-γ/IL-4 balance." (PMID 35584107, 2022). "This cytokine was shown to promote lung fibrosis, and IPF patients exhibited increased IL-4 and IL-13 receptors on lung fibroblasts." (PMID 34737752, 2021). "For a more thorough characterization and verification of the 10-4ABFP cells, cytokines elevated during pulmonary fibrosis (TGF-β1, IL-33, IL-4, and TSLP) were screened to establish dose- and time-response curves." (PMID 33162897, 2020). "It significantly suppressed the abnormal increase of interleukin-4 (IL-4) and TNF-α levels, increased the level of interferon-γ (IFN-γ), and contributed to the antifibrotic effects on pulmonary fibrosis by inhibiting TGF-β1 production in the lung." (PMID 33062025, 2020). "We also examined the levels of several other classical cytokines (including IFN-γ, IL-4, IL-12, IL-13) and several matrixmetalloproteinases (such as MMP2, MMP9) in this model of lung fibrosis." (PMID 26627341, 2015). "Other cytokines, such as connective tissue growth factor (CTGF), interleukin-4 (IL-4), interleukin-13 (IL-13) and endothelin etc., can cooperate with TGF-β to promote MF generation or proliferation, which, therefore, leads to pulmonary fibrosis." (PMID 24584660, 2014). "Secondly, we want to investigate the regulatory role of CD4+CD25+Foxp3+ Treg cells in silica-induced lung fibrosis by studying the mRNA expression of typical Th1 (IL-2, IFN-γ) and Th2 (IL-4) cytokines." (PMID 21072213, 2010). "We chose to test cytokines and factors known for their different activities on the development of lung fibrosis: proinflammatory (IL-1β and TNF-α), profibrotic (IL-4 and TGF-β) and antifibrotic mediators (IL-9 and PGE-2)." (PMID 16045809, 2005). "The presence of iNKT cells in WT mice might contribute to mitigating bleomycin-induced pulmonary fibrosis through mechanisms such as downregulating TGF-β 87 and inhibiting IL-4-driven M2 macrophage polarization." (PMID 39918959, 2025).
pulmonary fibrosis (continued). "Tocilizumab also could reduce the cytokine storm and the subsequent development of oedema and pulmonary fibrosis progression by decreasing VEGFA, IL-4 and especially TFGB1." (PMID 36791125, 2023). "Thus, iNKT cells protect mice from pulmonary fibrosis by (i) producing IFN-γ, thereby downregulating lung TGF-β levels and (ii) decreasing lung IL-4 levels, thereby inhibiting M2-macrophage activity." (PMID 37696892, 2023). "Results showed that LPSF/GQ-16 not only influenced the PBMCs’ production of IL-2, IL-4, IL-6, IL-17A, TNF, and IFN-γ, but also reduced skin thickening, downregulated biomarkers of skin and lung fibrosis, as well as decreased the activation of immune cells in the experimental model." (PMID 37833885, 2023). "By contrast, mIL‐33 may potentiate lung fibrosis by recruiting ST2L+M2‐macrophages and ST2L+ILC2s to enlarge Th2 cytokine milieu by excessive production of IL‐4, IL‐5, and IL‐13." (PMID 36082495, 2022). "Nonetheless, IL-13 seems to be the main fibrotic driver as on the one hand overexpression of IL-13 but not IL-4 induces spontaneous lung fibrosis and on the other hand IL-13-/- mice but not IL4-/- are protected from FITC-related fibrosis." (PMID 34093523, 2021). "Indeed, IL-4 levels were found to be significantly increased in the serum of patients with idiopathic pulmonary fibrosis and RILI, with the expression of collagen and fibronectin being significantly increased in fibroblasts treated with IL-4 in vitro." (PMID 33766127, 2021). "In this sense, the present study evaluated the histopathological features and immunohistochemical biomarkers (ACE-2, AKT-1, Caveolin-1, CD44v6, IL-4, MMP-9, α-SMA, Sphingosine-1, and TGF-β1 tissue expression) involved in the TGF-β1 signaling pathways and pulmonary fibrosis." (PMID 35008594, 2021). "In the bleomycin-induced mouse pulmonary fibrosis model, IL-4 and IL-13 levels were significantly increased, but after blocking the IL-4/IL-13 signaling pathway, the activation of STAT6 was reduced and which could significantly ameliorate pulmonary fibrosis." (PMID 34594474, 2021). "With this kind of results, it was further noticed that IL-4 mRNA levels and the IL-4 protein levels do not closely correlate in the late stages of the development of pulmonary fibrosis." (PMID 28512460, 2017). "This is in line with data in which IL-13 KO mice are protected from lung fibrosis but not IL-4 KO mice, despite the fact that they have abundant TGF-β1 levels." (PMID 27113293, 2016). "IL-13, IL-4 and IFN-γ were not significantly different in the myeloid PTEN deficient mice subjected to pulmonary fibrosis." (PMID 26971883, 2016). "While IL-1β, TNF-α and IL-4, known for their implication in the extension of lung fibrosis, had no or limited effect on Cat K expression, both concentrations of TGF-β1 (1 and 10 ng/ml) reduced Cat K expression." (PMID 16045809, 2005). "Despite the fact that overwhelming evidence exists regarding the role of type 2 immunity in lung fibrosis, these findings should be contrasted with the disappointing results of therapeutic trials of IL-13 and dual IL-4/IL-13 inhibition in IPF, which both failed to meet their therapeutic endpoints." (PMID 34093523, 2021). "IL-4-induced, macrophage-derived IGF-1 protects myofibroblasts from apoptosis via Akt signaling, which may contribute to the persistence of myofibroblasts in the Th2-deviated environment of pulmonary fibrosis." (PMID 30018981, 2018). "Despite pulmonary fibrosis is the main histopathological and radiological feature of chronic EAA, the role of IL-4 and IL-4R in EAA pathogenesis has not been studied yet." (PMID 23721656, 2013). "In agreement with this, we could show that IL-4 expression levels were elevated in the Fra-2 TG mouse model of SSc-ILD, but not in the bleomycin-induced model of lung fibrosis." (PMID 35332068, 2022).
viral infection (135 papers, 2005 to 2026). "The selective promotion of IFN-γ over IL-4 secretion also indicates a strategic benefit in possibly reducing the risk of Th2-mediated enhancement of viral infections, which can complicate vaccine efficacy." (PMID 39204016, 2024). "We have previously shown that the type 2 cytokines IL-4 and IL-13 enhance the susceptibility of KC to viral infection." (PMID 37298195, 2023). "Several groups have demonstrated that KC exposed to the type 2 cytokines IL-4 and IL-13 have increased susceptibility to viral infection." (PMID 37298195, 2023). "Previous observations by our group identified that KC have increased susceptibility to viral infection with VV after exposure to type 2 cytokines (IL-4 + IL-13)." (PMID 37298195, 2023). "The results showed that luteolin upregulated the expression of IFN-γ, downregulated the expression of TNF-α and IL-4, inhibited the inflammatory response caused by a viral infection, and improved the expression of interferon." (PMID 36830548, 2023). "In summary, we showed that keratinocyte differentiation state in tandem with inflammatory milieu (IL-4/13) or barrier disruption (TJDP treatment) critically alters susceptibility to viral infection." (PMID 35456017, 2022). "In fact, previous studies in viral infection showed similar results, with basophil level associated with humoral response and with IL-4 known to enhance B cell activity against infection." (PMID 34685733, 2021). "First, IL-13−/− and STAT-6−/− mice were far more susceptible to WT or mutant virus infection than IL-4−/− mice." (PMID 25751266, 2015). "We conclude that exposure to DE during an influenza infection polarizes the local immune responses to an IL-4 dominated profile in association with increased viral disease, and some aspects of this effect can be reversed with antioxidants." (PMID 21092162, 2010). "Also, pre-exposure to Cd exacerbates RSV (respiratory synical virus) infection outcomes with increased levels of IL-4 and fatty acid metabolism associated metabolites." (PMID 38168913, 2024). "Our group has also demonstrated that type 2 cytokines (IL-4 and IL-13) increase susceptibility to viral infection, further highlighting the complex interactions between the microbiome, host immune responses, and viral infection in AD." (PMID 37737609, 2023). "Our findings support the hypothesis that unique cytokine signatures present in the skin, e.g., subjects with the greatest expression of IL-4, IL-13, and IL-22, would be at most risk of experiencing disseminated viral infections." (PMID 37298195, 2023). "During the first trimester of pregnancy, the acute immune activation due to maternal viral infection increases the risk for having autistic children, and, at the time of birth, elevated levels of IL-1β and IL-4 in mothers have been associated to a subsequent diagnosis of ASD." (PMID 31616420, 2019). "Moreover, a number of cytokines, including IL-6, IL-6R, IL-21 and IL-4, have been implicated in shaping immune responses after viral infection." (PMID 27447555, 2016). "We proposed that one mechanism could be that immune responses to virus infection are type 1 deficient/type 2 augmented if they take place in a milieu rich in the type 2 cytokine IL-4 as occurs in atopic asthma." (PMID 16001979, 2005). "Other data to support the hypothesis that Th2-type responses increase susceptibility to virus infection include the observation that PBMC from Kenyan schistosomiasis patients with HIV-1 coinfection produce decreased levels of IL-4 and IL-10 compared to patients with schistosomiasis alone." (PMID 18648516, 2008). "dupilumab, by competitively inhibiting IL-4 and IL-13 binding to IL-4Rα, attenuates Th2 cytokine-mediated enhancement of IL-8 production induced by dsRNA or viral infection in epithelial cells." (PMID 41576028, 2026). "The next step was performing a classical ELISA for representative cytokines important for viral infection—IL-4, IL-5, IL-6, IL-10, IL-17, and TNF alpha." (PMID 40358160, 2025).
viral infection (continued). "Our stimulation panel included stimuli that trigger pro- and anti-inflammatory pathways in macrophages (IFNβ, IFNγ, interleukin-4/IL4) and those that induce response to viral infection (Resiquimod/R848, Poly I:C/PIC)." (PMID 40866338, 2025). "The effect of basal IL-4 on Arg1 expression and pathology suggests that additional signals derived from the virus infection, or the immune response to it, are likely required to combine with IL-4 for the effects seen." (PMID 40854598, 2025). "To the extent of what we know, the data are contrasting about the kinetics of IL-4 in humans following viral infection and they appear to be virus-specific." (PMID 38543749, 2024). "It was noteworthy that the asthmatics with respiratory viral infections showed delayed but lasting Th2 airway response, as evidenced by accumulated upregulation of IL-4 and IL-5 levels until day 14 upon viral infections." (PMID 37865742, 2023). "In response to most viral infections, B cells can bind to viral proteins through their antigen receptors, by secreting effector molecules (IL-2, IL-4, IL-6, IFN-γ, TNF-α) to help contain viral infections." (PMID 35774402, 2022). "This can be correlated with the increased levels of IL-4 and IL-9, found in the plasma of these patients and is generally unproductive in protecting against viral infections." (PMID 35572555, 2022). "WT infected patients also showed higher IL-17+ CD4+ T cells but with lower IL-4+/IL-6+ CD4+ T cells compared to patients with mutant virus infection." (PMID 34716845, 2022). "Our data demonstrate a clear increase in IFN-γ in relation to other cytokines (IL-2 and IL-4) in the brain of surviving animals, corroborating the contribution of this cytokine to viral infection control and protection." (PMID 36679918, 2022). "JNK signaling pathway was suggested to play a prominent role in immune response to viral infection due to activation of several interleukins (IL-2, IL-4) and IFN-γ." (PMID 35213582, 2022). "Before administration, expression levels of IFN-γ and IL-4 in the prevention group were significantly up-regulated than those of the virus infection group." (PMID 35255906, 2022). "High cytokine IL-4 was present at 1 to 3 months in individuals recovering from the initial viral infection." (PMID 35625737, 2022). "CD8+/CD25+ cells are induced by viral infection and some mechanisms dependent on IL-4 and IL-12, and they regulate Th1/Th2 reactions by production of IL-10 and IFNγ." (PMID 35337377, 2022). "CD4+ T cells are activated via the secretion of Th2-related cytokines (IL-4, IL-5) to stimulate B cells for the production of antibodies to prevent viral infection." (PMID 35632667, 2022). "Namely, JNKs are important kinases that are activated in innate immune responses to viral infection and stimulate the activity of several significant cytokines, including interleukins (IL-2, IL-4)." (PMID 34988113, 2021). "The role of IL-2 and IL-4 is to resist viral infection, activate T cells, promote B cell proliferation, and secrete antibodies." (PMID 33390949, 2020). "The adjuvant and vaccine induced an upregulation of IL-4/13 at later time points, and virus infection in vaccinated and naïve fish resulted in a prolonged upregulation starting at 3 dpi." (PMID 33276596, 2020). "Th2, which controls humoral immunity, is effective for protection against most bacterial and several viral infections and is characterized by the formation of cytokines IL-4 and IL-10 and enhanced production of IgG1." (PMID 32168741, 2020). "We postulated that one possible explanation for the limited enhancement by IL-4/IL-13 of virus infection in pmacs is that other receptors utilized by EBOV are also available and utilized in pmacs." (PMID 31825972, 2019). "With the demonstration that expression of human DC-SIGN, murine SIGNR3 and MGL was increased in IL-4/IL-13-stimulated macrophages, we assessed the effect of these receptors on virus infection using carbohydrate-based competitors." (PMID 31825972, 2019).